SHMT2 (serine hydroxymethyltransferase 2)
Diseases named in the same sentence as SHMT2 in open-access papers (continued):
Sharing a sentence is not in itself a finding about the gene and the disease.
tumor (continued). "This evidence was confirmed by the analysis of the histological score, obtained by a combination of the SHMT2 intensity expression and the percentage of the tumor sample positive for its expression." (PMID 36964165, 2023). "The key metabolic enzymes are SHMTs, of which SHMT2 (mitochondria) is upregulated in a variety of tumors and closely related to tumor progression and patient survival." (PMID 36806313, 2023). "Collectively, SHMT2 reduction inhibited HIF1α expression in the tumor tissue, reduced tumor malignancy, and slowed tumor cell proliferation in vivo." (PMID 37108312, 2023). "NOTCH1-mutated tumours did show higher expression of serine/glycine metabolism enzymes PHGDH, SHMT1 and SHMT2." (PMID 36932191, 2023). "Clinical studies have also shown that high SHMT2 expression is closely related to tumor invasion and prognosis." (PMID 37108312, 2023). "Over recent years, relevant studies have shown that SHMT2 (serine hydroxymethyltransferase 2), a key enzyme of serine metabolism, is involved in the occurrence and development of tumors and in the regulation of tumor cell proliferation." (PMID 35211429, 2022). "We assessed SHMT2 expression by qPCR in five newly collected pairs of normal and tumor tissues from CRC patients." (PMID 35211429, 2022). "SIRT5 catalyzes the desuccinylation of the serine metabolic enzyme SHMT2 to regulate one-carbon metabolism and promote tumor proliferation." (PMID 36577755, 2022). "More recently, another serine biosynthesis enzyme, SHMT2, was reported to initiate lymphoma development by epigenetically silencing tumor suppressors." (PMID 34050894, 2022). "Clinical decisions should be based on the different molecular subtypes of pRCC; therefore, sensitivity to the 30 common anti-tumour drugs was compared between the high– and low–SHMT2 expression groups to determine potential treatment modalities for pRCC." (PMID 36110969, 2022). "The expression of PSPH and SHMT2 was significantly higher in tumour tissues, whereas PHGDH and PSAT1 were reduced." (PMID 36110969, 2022). "Since hypersuccinylation of SHMT2 inhibits its enzymatic activity, SIRT5 can enhance the promotion of SHMT2 on tumor proliferation." (PMID 36699468, 2022). "Taken together, we demonstrated that SHMT2 is an important factor driving tumor metastasis and invasion in OSCC." (PMID 35333683, 2022). "This transactivation activity probably accounts for the ability of SHMT2 to serve as a biomarker for tumor progression and poor prognosis." (PMID 35211429, 2022). "The results demonstrated that the IC50s of the 22 anti-tumour drugs were significantly different in the two SHMT2 expression groups." (PMID 36110969, 2022). "Targeting 1C metabolism has the potential to inhibit malignant tumor behaviors, as shown by the effects of drugs targeting Mthfd2, Shmt2, and Mettl3." (PMID 34298902, 2021). "Immunoblot analysis of lysates obtained from surgical samples of 6 GBM patients confirmed increase of MTHFD2 and SHMT2 expression in tumor tissues relative to normal brain tissues." (PMID 33468252, 2021). "More importantly, both primary and metastatic tumour growth was suppressed in the SHMT2 knockdown group." (PMID 34476002, 2021). "Intriguingly, in CRC, SIRT3 displays an oncogenic role by deacetylating SHMT2, and acts as tumor suppressor by increasing ROS production and PINK1/Parkin/mitophagy axis activation." (PMID 34680344, 2021). "SHMT2 knockdown significantly prevented tumor growth with an inhibition rate of 70-81% in both HCT116 and DLD-1 cell mouse models." (PMID 33456583, 2021). "SHMT2 has a role in folate metabolism, as it provides active one-carbon unit contributing to the biosynthesis of nucleotides and proteins involved in tumour growth." (PMID 34476002, 2021). "The prevention of tumour development, metastasis and recurrence by the perturbation of specific SHMT2 inhibitors requires further exploration." (PMID 34476002, 2021).
tumor (continued). "Glycine can also be utilised, under serine limitation, as substrate of the enzyme SHMT2 to support serine synthesis, a crucial amino acid for tumour cell proliferation." (PMID 34944586, 2021). "A high SHMT2 expression is correlated with the tumor histological grade of BLCA and predicts a poorer overall survival." (PMID 34149818, 2021). "First, we found that SHMT2 was highly expressed in all most tumor tissues base on the TNMplot database." (PMID 34149818, 2021). "SHMT2 has also been shown to affect cell proliferation under certain stress scenarios such as in tumor ischemic regions." (PMID 32903271, 2020). "In order to test the effects SHMT2 expression on tumor formation in vivo, HeLa-Ss cells were implanted in immune deficient mice." (PMID 32903271, 2020). "In the context of the HeLa-Ss inducible system, induced ectopic over-expression of SHMT2 was sufficient to increase tumor cell proliferation in vitro and in vivo." (PMID 32903271, 2020). "Multiple studies show that SHMT2 plays critical roles in tumor growth and progression in a variety of cancer types, especially in tumors with Myc protein highly expressed." (PMID 34766113, 2020). "Genetic or pharmacologic inhibition of SHMT2 renders reduced tumor growth or lengthens survival of tumor‐bearing mice." (PMID 34766113, 2020). "Intriguingly, the outcome shows that Module Blue, which contains SHMT2, was strongly correlated with gender, tumor stage, and especially pathological grade." (PMID 33163414, 2020). "SHMT2-dependent NADPH production maintains redox balance to support tumor cell survival and proliferation." (PMID 32903271, 2020). "Further, SHMT2 expression was detected in ischaemic tumor regions, thereby procuring a proliferative advantage under hypoxia." (PMID 32365833, 2020). "Downregulating SHMT2, either by shRNA knock down, SHMT2 silencing, or inhibition using L-mimosine, suppressed tumor growth and increased chemotherapeutic sensitivity." (PMID 32111066, 2020). "SHMT2 is the main source of glycine in proliferating cells and its importance for tumor cells survival in hypoxia was demonstrated in glioblastoma multiforme (GM)." (PMID 30857125, 2019). "PKM2 and SHMT2 levels can play an important role in regulating the metabolic switch and tumor progression." (PMID 31500219, 2019). "High SHMT2 expression was observed in 52 tumor specimens of the total 100 cases, according to previous criteria." (PMID 30228815, 2018). "The results showed that SHMT2 level was notably increased in tumor samples compared to paired controls." (PMID 30228815, 2018). "Of these 35 pairs of samples, 27 tumor samples exhibited a significant increase in the steady-state level of SHMT2 protein (P < 0.001), and the K95 acetylation level of SHMT2 was invariably reduced in all tumor samples with high SHMT2 expression." (PMID 30367038, 2018). "In this study, we observed that the expression level of SHMT2 is significantly increased in patient tumor samples and is correlated with poorer overall postoperative survival." (PMID 30367038, 2018). "We used tetracycline-inducible SHMT2-knockdown tumor xenograft mouse model to inhibit SHMT2 expression at certain tumor sizes in order to mimic clinical situation." (PMID 27391339, 2016). "In this study, we used a tetracycline-inducible SHMT2-knockdown tumor xenograft mouse model to demonstrate that inhibiting SHMT2 reduces tumor incidence as well as tumor growth." (PMID 27391339, 2016). "On the other hand, SHMT2-overexpressed 3T3 mouse embryonic fibroblast cells did indeed generate tumor xenograft after inoculation into nude mice, albeit at a low incidence rate (1 out of 6 mice)." (PMID 27391339, 2016). "To validate the in vitro results in an animal model, we tested the efficacy of SHMT2 inhibition in arresting tumor development by implanting these cells subcutaneously in nude mice." (PMID 27391339, 2016).
tumor (continued). "We also explored relationships between high SHMT2 level and negative prognosis, finding that elevated SHMT2 levels were significantly associated with larger tumor size, positive lymph node metastasis, and advanced TNM stage." (PMID 40432803, 2025). "It is believed that the overexpression of the enzymes SHMT2 and HAS2 with AGL loss drives increased synthesis of glycine and hyaluronic acid, leading to enhanced glucose absorption and metabolism that promotes rapid tumor proliferation and growth." (PMID 39858027, 2025). "In addition to its metabolic functions, SHMT2 expression influences the tumor immune microenvironment." (PMID 40738465, 2025). "Clearly, the situation may turn out to be different in rapidly dividing tumor cells with their elevated demand of nucleotides, which also frequently induce serinogenesis and the mitochondrial folate-metabolizing enzymes SHMT2 and MTHFD2." (PMID 41373508, 2025). "Notably, SHMT2 expression increased as tumor cells became less differentiated and was inversely correlated with the thyroid differentiation score." (PMID 40738465, 2025). "In addition, high USP32 expression plays a crucial role in tumor growth, metastasis, immune infiltrates, and chemoresistance via the deubiquitination of various substrate proteins, such as Smad2, SHMT2, FDFT1, Rab7, SLC35F2, and BAG3." (PMID 40136417, 2025). "The findings underscored the capacity of SHMT2 as a therapeutic target, as inhibiting its activity could disrupt these critical pathways, reducing tumor growth and metastasis." (PMID 40432803, 2025). "Further research has indicated that TWIST, an important transcription factor closely associated with tumor invasiveness and metastasis, may upregulate SHMT2 expression, driving tumor invasion and metastasis." (PMID 40738465, 2025). "Moreover, SHMT2 alters DNA methylation patterns, thereby regulating the expression of tumor-related genes, highlighting its role in the epigenetic regulation of CRC progression." (PMID 40738465, 2025). "On the contrary, SHMT2 isoforms 3 might function as tumor promoting function to promote CSC-like features." (PMID 40097394, 2025). "With continued progress in miRNA delivery methods, miRNAs targeting SHMT2, such as miR-383-5p, may also have value as tumor-targeted therapeutic agents." (PMID 38577602, 2024). "The expression of SHMT2 was correlated with tumour size (P = 0.034) and, TNM stage (P = 0.042)." (PMID 38188143, 2024). "In addition, the high expression of SHMT2, advanced T stage, M stage, pathological grade, tumor size, vessel invasion and TNM stage predicted the poor prognosis with GC patients." (PMID 38188143, 2024). "Importantly, PTEN mRNA levels were lower in tumor tissues with high SHMT2 expression than in specimens with low SHMT2 levels." (PMID 38272883, 2024). "Recently, the cytoplasmic isoform of SHMT2 was identified as a driver of tumor progression." (PMID 38272883, 2024). "In addition, SHMT2 is involved in certain processes of tumorigenesis and development and is associated with the expression of MIF, CD74, CXCR4 and CD44 in the HNSCC tumor microenvironment." (PMID 38625586, 2024). "Importantly, the levels of phosphorylated-AKT (Ser 473) were higher in tumor samples with high SHMT2 expression than in those with low SHMT2 expression." (PMID 38272883, 2024). "In addition, we revealed that SHMT2 was obviously higher in tumor tissues with high TNM stage (III-V) than those with low stage (I-II)." (PMID 37932821, 2023). "Therefore, SHMT2 is expected to be an important target for tumor metabolic reprogramming, and further exploration of its role in tumors is needed." (PMID 37108312, 2023). "Notably, both MYC expression and m6A levels of nude mice tumor tissues were reduced in the SHMT2 knockdown group." (PMID 37932821, 2023). "While SHMT2 overexpression had the opposite effects, promoting tumor progression." (PMID 36806313, 2023).
tumor (continued). "Additionally, the expression of EMT-related markers was also reduced in the tumor tissue, as SHMT2 was found to have an effect on EMT in vitro, and the expression of EMT-related markers N-cadherin and vimentin were reduced in the tumor." (PMID 37108312, 2023). "Interestingly, SHMT2 is expressed in all cBCC cells, in contrast to cSCC, where SHMT2 is significantly downregulated in the more differentiated areas of the tumor." (PMID 36964165, 2023). "Undoubtedly, the protein level of SHMT2 was visibly increased in tumor tissues." (PMID 37932821, 2023). "Finally, a xenograft tumor nude mouse model was conducted to verify the role and mechanism of SHMT2 in vivo." (PMID 37932821, 2023). "In cBCC representative samples SHMT2 was detected in all tumor cells, in contrast to cSCC representative samples where the expression of SHMT2 decreased in the differentiated area of the tumor." (PMID 36964165, 2023). "SHMT2 was found to enhance T cell mediated tumor killing effect." (PMID 37932821, 2023). "Finally, silencing SHMT2 significantly reduced tumor growth and decreased stemness markers in a xenograft model." (PMID 36077112, 2022). "SHMT2 depletion led to a profound reduction of tumor growth compared with controls." (PMID 35211429, 2022). "In addition, considerably higher SHMT2 protein expression was detected in all four tumor tissues relative to the normal tissues obtained from the same patients." (PMID 36077112, 2022). "In addition, SMGs, especially SHMT2, exacerbated the carcinogenesis and immunosuppressive cells in pRCC, thus promoting tumour proliferation." (PMID 36110969, 2022). "Furthermore, we found that silencing SHMT2 inhibited the expression of stemness markers and tumor spheroid formation compared with a control group." (PMID 36077112, 2022). "The results of the present study provide novel insights into the biology of CRC cells and suggest that SHMT2 may be a potential target for tumor therapy." (PMID 35211429, 2022). "Moreover, the expression of SHMT2 is related to the clinicopathological characteristics of the tumor, such as the patient’s age and tumor stages." (PMID 36699468, 2022). "Because of its significant overexpression in tumour tissues and poor prognosis in survival analysis, it was hypothesised that SHMT2 might play a role in the tumourigenesis and progression of pRCC." (PMID 36110969, 2022). "Furthermore, the effects of knocking down SHMT2 expression on tumor cell clonogenicity were examined." (PMID 36077112, 2022). "A growing body of researches have exposed that SHMT2 contribute to tumor migration and invasion." (PMID 35333683, 2022). "The ability of metformin to either improve or impede the therapeutic response of tumor cells to serine and glycine starvation might also be reconsidered, at least in part, in terms of the direct SHMT2-targeted effects of metformin." (PMID 34439169, 2021). "In addition to the effect on tumor growth, the impact of SHMT2 on CRC metastasis was also evaluated in vivo using the intrasplenic-nude mouse model system (ISMS)." (PMID 33456583, 2021). "Silencing SHMT2 in the HN6 cell line using short hairpin RNA also impeded tumor growth in vivo." (PMID 33863325, 2021). "However, aberrant SHMT2 promoted changes in metabolism that enhanced the survival capacities of tumour cells to survive in the ischaemic microenvironment." (PMID 34476002, 2021). "In addition, SHMT2 expression was higher in patients with a high tumor grade and in those who were older than 60 years." (PMID 34149818, 2021). "Additionally, Yang and his colleagues proved that down regulating of SHMT2 suppresses the proliferation of the colon colorectal carcinoma cells and hinders the tumor cell growth in vitro and vivo." (PMID 33863325, 2021). "Studies on noncoding RNAs in tumours have been increasing in recent years, and it was also reported that SHMT2 could be directly and negatively regulated by miR-370 in human articular chondrocytes and miR-615-5p in HCC cells." (PMID 34476002, 2021).
tumor (continued). "Moreover, clinical significance analysis revealed that high expression of SHMT2 was significantly correlated with advanced pathologic tumor stage, lymph node metastasis and advanced clinic stage." (PMID 33863325, 2021). "Different studies suggest the diverse functions of SHMT2 in the majority of tumours." (PMID 34476002, 2021). "SIRT3 and SIRT5 also mediate desuccinylation and deacetylation of SHMT2, respectively, suggesting that suppression of serine catabolism might represent a novel strategy to restrain tumor growth." (PMID 33117804, 2020). "Ectopic over-expression of SHMT2 increased cell proliferation in vitro and tumor growth in vivo." (PMID 32903271, 2020). "Moreover, it has been proved that downregulation of SHMT2 can inhibit tumor occurrence rate and growth." (PMID 33163414, 2020). "This modification seems to be critical for SHMT2 active involvement in tumor growth." (PMID 30857125, 2019). "Furthermore, the data demonstrated a correlation between SHMT2 expression and tumor aggressiveness (TNM stage) in iCCA." (PMID 30228815, 2018). "Interestingly, most tumor samples with high SHMT2 expression exhibited increased SIRT3 protein expression compared with adjacent normal tissues (P < 0.01)." (PMID 30367038, 2018). "Furthermore, SHMT2 expression is significantly related with tumor T stage (P = 0.017) and tumor TNM stage (P = 0.041) in patients with iCCA, disregarding age, gender, tumor size, tumor number, pathological grade, vascular invasion, or lymph node metastasis." (PMID 30228815, 2018). "Notably, SHMT2 is required for survival and proliferation of neoplastic cells in ischemic tumor zones." (PMID 30197878, 2018). "Highly expressed SHMT2 provides an advantage to tumor cells in poorly vascularized tumor regions." (PMID 28515048, 2017). "Similarly, inducible SHMT2 inhibition, via doxycycline-added drinking water, was found to reduce tumor incidence and tumor growth in a human tumor xenograft mouse model." (PMID 27391339, 2016). "The secondary objective was to lead credence to the hypothesis that AGL affects tumor biology by RHAMM downstream of HAS2/HA axis as well as other effectors such as SHMT2." (PMID 27595989, 2016). "While SHMT2 has been implicated in tumor genesis in mice, no prior study has linked it to BaP exposure directly." (PMID 23403841, 2012). "Besides, knockdown of SHMT2 significantly inhibit tumor proliferation." (PMID 40432803, 2025). "This means that SHMT2 may also play a role in tumour growth and metabolism." (PMID 38188143, 2024). "However, the mechanism of tumour progression mediated by SHMT2 is still poorly explored." (PMID 38188143, 2024). "Interestingly, comprehensive data from Wang’s and our own datasets indicate that SHMT2 might enhance ccRCC tumorigenesis while impairing tumor thrombus invasion, whereas CADM4 possibly exerts opposite effects on tumorigenesis and thrombus invasion." (PMID 37328520, 2023). "Moreover, we also measured the link between SHMT2 and tumor immune." (PMID 37932821, 2023). "Indeed, we found that the expression of metabolic enzymes MTR, AHCY, and SHMT2 was elevated in tumorspheres compared to adherent tumor cells, which supports the idea that hypoxia is a key factor in altering the pattern of one-carbon metabolism in tumorsphere cells." (PMID 39872059, 2023). "Moreover, RNA sequencing from 4 normal head and neck tissue samples and 43 HNC tissue samples (10 oral cavity, 5 oropharynx, 28 larynx) from the CNUH data was conducted, and we found that the SHMT2 expression levels were significantly higher in tumor tissues than in normal tissues." (PMID 36077112, 2022). "Likewise, in this study, we demonstrated that the expression of SHMT2 in HNC tumor tissues and cell lines was elevated, and its overexpression was also positively related to the histological grade, lymph node metastasis, distant metastasis, AJCC stage, and lymphovascular invasion." (PMID 36077112, 2022).